DPP4 (dipeptidyl peptidase 4)
Diseases named in the same sentence as DPP4 in open-access papers (continued):
Sharing a sentence is not in itself a finding about the gene and the disease.
heart failure (continued). "Some studies even have suggested that DPP4 inhibitors may reduce the risk of heart failure." (PMID 28756774, 2017). "Therefore, whether the most commonly used DPP-4 inhibitor, sitagliptin, may increase the risk of heart failure is under-investigated and inconclusive." (PMID 27409676, 2016). "A study in a heart failure mouse model found that DPP-4 inhibitors, through the GLP-1 receptor signaling pathway, improved mitochondrial biogenesis in skeletal muscle, thereby enhancing exercise capacity." (PMID 41018201, 2025). "The mechanism proposed for increased incidences of cardiac failure hospitalization was related to elevated concentration of the DPP4 substrates, substance P and Neuropeptide Y, both of which increase heart rate by increasing sympathetic activity." (PMID 39861115, 2025). "One possible mechanism to explain the worsening of heart failure in patients taking DPP-4 inhibitors is sympathetic overactivity through potentiation of endogenous stromal cell-derived factor 1, neuropeptide Y, and substance P." (PMID 40141772, 2025). "Therefore, while some DPP-4 inhibitors such as Saxagliptin may cause worsening of heart failure events, Sitagliptin, and particularly Linagliptin has significant clinical data available to suggest a good safety profile, albeit with no significant cardiovascular benefits." (PMID 39911238, 2024). "Clinical trials such as SAVOR-TIMI 53, EXAMINE, and TECOS are evaluated to provide a comprehensive analysis of DPP-4 inhibitors’ effects on hospitalization for heart failure, mortality, and cardiovascular events in diabetic patients." (PMID 39768866, 2024). "In summary, this review synthesizes available evidence on DPP-4 inhibitors’ impact in diabetic patients with heart failure, aiming to guide clinicians in making informed therapeutic decisions." (PMID 39768866, 2024). "Other mouse studies modeling heart failure have shown increased cardiac function and decreased diastolic dysfunction with DPP‐4 inhibitors." (PMID 38472161, 2024). "When evaluating DPP-4 inhibitors in the context of heart failure, it is crucial to consider their effects on heart function and related outcomes." (PMID 39768866, 2024). "On the other hand, there are also conflicting reports that DPP-4 inhibitors contribute to improved long-term cardiac outcomes in individuals with heart failure with a preserved ejection fraction." (PMID 38256615, 2024). "Nonetheless, concerns regarding the cardiovascular safety of DPP-4 inhibitors in heart failure emerged after some agents showed adverse outcomes in cardiovascular trials." (PMID 39768866, 2024). "Despite these mechanisms, DPP-4 inhibitors have produced mixed results in heart failure outcomes across clinical trials." (PMID 39768866, 2024). "In patients with heart failure, DPP-4 expression and activity can be affected, and studies suggest a potential overexpression of the enzyme in the cardiac and endothelial tissues in heart failure conditions." (PMID 39768866, 2024). "The EXAMINE trial also highlighted gaps in understanding the mechanistic effects of DPP-4 inhibition on the cardiovascular system, particularly concerning heart failure." (PMID 39768866, 2024). "A swine study using heart rate‐induced heart failure showed increased stroke volume with DPP‐4 inhibitor treatment." (PMID 38472161, 2024). "The findings suggested a significant increase in hospitalisation for heart failure events with the DPP-4 inhibitor." (PMID 39911238, 2024). "SGLT-2 inhibitors had reduced hazards of hospital admission for heart failure compared with DPP-4 inhibitors (0.32, 0.12 to 0.90) and sulfonylureas (0.46, 0.20 to 1.05)." (PMID 38719492, 2024). "SGLT-2 inhibitors have a lower all-cause mortality rate compared with DPP-4 inhibitors and GLP-1R agonists, especially in terms of cardiovascular mortality and hospitalization for heart failure." (PMID 37686185, 2023).
heart failure (continued). "A recent meta-analysis by Sinha and Ghosal that included data from four of these trials reported neutral effects of DPP4 inhibitors on hospitalisation for heart failure (OR 1.06 (95% CI 0.96–1.18))." (PMID 34097240, 2022). "DPP-4 activity is relatively high in patients with heart failure and thus modulates the pathophysiology of heart failure by acting on its substrate." (PMID 35164839, 2022). "It has been reported that BNP activity is modulated by DPP-4 in diabetic subjects with heart failure." (PMID 35164839, 2022). "The possible dangerous cardiovascular side effects of DPP4 inhibitors are included in the latest ESC heart failure guideline, which suggests avoiding the administration of gliptins in diabetic patients with heart failure." (PMID 35884882, 2022). "DPP-4 inhibitors have a favorable safety profile among older persons although caution is needed in patients with heart failure, and dose reduction is needed in renal impairment." (PMID 34911481, 2021). "Numerous lines of proofs from experimental and clinical studies have showed that the favorable properties of DPP4 inhibitors on the progression of heart failure connected with poorer cardiovascular outcomes, especially DD." (PMID 34489872, 2021). "Factors associated with a higher incidence of ACEi-AE include female gender, African American ethnicity, heart failure diagnosis, and concomitant therapy with immunosuppressants or dipeptidyl peptidase-IV (DPP-4) inhibitors." (PMID 34692327, 2021). "Despite a neutral effect on the primary outcome of 3-point MACE, an area of potential concern arising from the completion of DPP-4 inhibitor CVOTs relates to the secondary outcome of rates of hospitalization due to heart failure." (PMID 33364978, 2020). "In contrast to DPP-4 inhibitors and GLP-1 agonists, the SGLT2 inhibitors canagliflozin, dapagliflozin, and empagliflozin reduced the risk of heart failure in the CANVAS, DECLARE–TIMI, and EMPA-REG OUTCOME trials, respectively." (PMID 31832207, 2019). "In a related commentary, one possible explanation was proposed that the unexpected findings from SAVOR TIMI-53 was due to chance, and that the overall CV effects of DPP-4 inhibitors (including heart failure) were likely neutral." (PMID 30961600, 2019). "Our results suggest that DPP-4 inhibitors or GLP-1 RAs improve exercise tolerance in heart failure patients." (PMID 31870322, 2019). "In conclusion, dapagliflozin, when compared with DPP‐4 inhibitor treatment, was associated with a lower risk of MACE, heart failure and all‐cause mortality in a real‐world T2D population, where 23% had previously established CV disease." (PMID 28771923, 2018). "Using DPP-4 inhibitors as a therapy in different models of heart failure resulted in improvements in the severity of HF, survival, and remodeling of the ventricle." (PMID 30343339, 2018). "Further, emerging evidence from preclinical and clinical studies support that DPP-4 inhibitors ameliorate the development and progression of heart failure." (PMID 29669555, 2018). "Plasma levels of dipeptidyl peptidase-4 (DPP-4) have been correlated with both human cardiac dysfunction and animal models of heart failure, highlighting the potential direct link between CV health and DPP family." (PMID 30343339, 2018). "Two recently published observational studies concluded DPP4 inhibitors had similar risks of heart failure as other antidiabetic medications." (PMID 28756774, 2017). "Dipeptidyl-peptidase-4 inhibitors are well known to enhance endogenous GLP-1 levels, but the risk of heart failure is also increased." (PMID 28282854, 2017). "The objective was to assess relative risk of heart failure hospitalization of sodium–glucose co-transporter-2 (SGLT2) and dipeptidyl peptidase-4 (DPP4) inhibitors in T2DM patients." (PMID 28756774, 2017). "DPP-4 inhibitors can decrease the incidence of atherosclerosis and reduce infarct size, improve heart failure, and improve cognitive function." (PMID 29100378, 2017).
heart failure (continued). "There are GLP-1 receptors on the heart and questions were raised in view of the DPP-4 inhibitor results on heart failure; there is a mild, but consistent, increase in heart rate with all GLP-1 agonists." (PMID 29270438, 2017). "The applicability of these findings to clinical heart failure remains uncertain and direct beneficial CV effects of DPP-4 inhibitors in patients with T2D are yet to be proven." (PMID 28903775, 2017). "The cardiovascular safety of DPP4 inhibitors, especially in heart failure, has been questioned since 2013 when the first 2 large clinical trials assessing the cardiovascular safety of DPP4 inhibitors (EXAMINE and SAVOR-TIMI 53) were completed." (PMID 28619058, 2017). "Heart failure is also associated with elevated circulating DPP-4 levels, and DPP-4 activity increases with the progression of heart failure." (PMID 28771625, 2017). "In contrast, some cardiovascular outcome studies revealed increased hospitalization rates for heart failure among a subset of DPP4 inhibitor-treated diabetic subjects." (PMID 27496100, 2016). "The investigators showed an increase of approximately 130% in circulating DPP-4 activity in patients with heart failure and an inverse correlation between serum DPP-4 activity and left ventricular ejection fraction in patients with heart failure." (PMID 27409676, 2016). "Animal studies have suggested that DPP4 inhibition improved cardiac function and survival rate of heart failure." (PMID 26075284, 2015). "Using optimized sampling, we measured DPP4 activity and SDF1α levels in patients with varying degrees of heart failure." (PMID 26544044, 2015). "Patients with severe LV dysfunction had significantly higher SDF1α concentrations DPP4 activity was similar in all of the investigated heart failure subgroups." (PMID 26544044, 2015). "This is in contrast with recent data demonstrating increased DPP4 activity levels in patients with heart failure." (PMID 26544044, 2015). "The possible value of DPP4 activities and SDF1α levels as biomarkers for heart failure was also evaluated." (PMID 26544044, 2015). "Secondly, the use of SDF1α and DPP4 as biomarkers were analyzed in patients with varying degrees of heart failure." (PMID 26544044, 2015). "Even an increased cardiovascular risk for DPP4 inhibitors was discussed, since in the SAVOR-TIMI 53 trial, a significant increased hospitalization due to heart failure in the saxagliptin-treated group was observed." (PMID 26284071, 2015). "In recent years, DPP4 activity and SDF1α have been suggested as possible biomarkers for heart failure." (PMID 26544044, 2015). "DPP4 inhibitor exhibited significant attenuation of heart failure related dysfunction and remarkably mitigated pulmonary congestion." (PMID 24416433, 2014). "An investigation into the use of DPP-4 inhibitors in patients undergoing cardiac surgery is necessary due to the increased use of these drugs in the recent decades and its controversial effects on heart failure." (PMID 40141772, 2025). "Plasma DPP4 activity correlated with cardiac dysfunction in animal and human with heart failure." (PMID 39968759, 2025). "While DPP4 inhibition is generally beneficial in myocardial infarction, it may worsen outcomes in advanced heart failure through mechanisms such as sympathetic activation and fibrosis." (PMID 41141478, 2025). "Similarly, linagliptin, another DPP-4 inhibitor, has shown a neutral cardiovascular safety profile in heart failure patients, supporting its use in this population." (PMID 39768866, 2024). "This trial added to a growing body of evidence indicating that while DPP-4 inhibitors are safe in terms of MACEs, there may be nuanced effects on heart failure outcomes that warrant further exploration." (PMID 39768866, 2024).
heart failure (continued). "This review aims to delve into the physiological underpinnings of DPP-4 inhibitors, analyze their clinical efficacy and safety for heart failure patients, explore the unique considerations for special populations, and compare them to other antidiabetic therapies in this high-risk group." (PMID 39768866, 2024). "Studies that examine the impact of DPP-4 inhibitors on biomarkers of heart failure and myocardial function could further refine our understanding of the relationship between DPP-4 inhibition and cardiac health." (PMID 39768866, 2024). "This study furthers our understanding of how DPP‐4 inhibitors could exacerbate heart failure and provides targets for further investigation in humans." (PMID 38472161, 2024). "However, recent studies have found that DPP4 inhibitors have major side effects, such as gout symptoms, infectious diseases, venous thrombosis, heart failure, myocardial infarction, and stroke in diabetic patients." (PMID 38424257, 2024). "The variation in heart failure outcomes observed across DPP-4 inhibitors may be attributed to differences in enzyme-binding affinity, pharmacokinetics, and off-target effects." (PMID 39768866, 2024). "However, as has been formerly shown, the use of DPP4 inhibitors can lead to worsening heart failure in patients with established cardiovascular disease or metabolic abnormalities." (PMID 38534765, 2024). "Thus, most animal trials have shown cardiovascular benefits with DPP4i, although one mouse study showed worsening heart failure with DPP‐4 inhibitor treatment." (PMID 38472161, 2024). "In addition, cumulative use of DPP4 inhibitors significantly increased the incidence of heart failure, myocardial infarction and stroke in diabetic patients." (PMID 38424257, 2024). "However, the relationship between DPP-4 inhibition and heart failure outcomes remains complex and has shown variable results in clinical trials." (PMID 39768866, 2024). "The choice of DPP-4 inhibitor should, therefore, consider these differences and prioritize agents with proven safety profiles, such as sitagliptin and linagliptin, in patients with heart failure." (PMID 39768866, 2024). "Moreover, geographic differences exist in adverse outcomes, with studies in Taiwan, Hong Kong, and the United States showing higher incidences of heart failure, hyperlipidemia, and renal failure with DPP-4 inhibitors compared to biguanides." (PMID 39121166, 2024). "For example, there is concern that DPP-4 inhibitors may promote adrenergically mediated cardiotoxicity, leading to heart failure events." (PMID 38256615, 2024). "This upregulation of DPP-4 has critical implications for heart failure pathophysiology." (PMID 39768866, 2024). "The increased expression of DPP-4 in heart failure may therefore contribute to worsened outcomes by blunting these beneficial GLP-1-mediated effects." (PMID 39768866, 2024). "Future research aimed at understanding the exact role of DPP-4 expression in heart failure and differentiating the effects of specific DPP-4 inhibitors could help clarify their role in this patient population and optimize their safe application." (PMID 39768866, 2024). "Moreover, the use of dipeptidyl peptidase-4 (DPP-4) inhibitors has been shown to result in an increased number of heart failure events in randomized clinical trials, and intake was associated with more heart failure events in observational studies." (PMID 37111578, 2023). "Moreover, given that treatment with saxagliptin has been associated with increased risk hospitalization for heart failure, we cannot exclude that DPP-4 inhibitors are prescribed with caution in older diabetic patients with heart failure." (PMID 36964858, 2023). "Three large, randomized-controlled trials showed that DPP-4 inhibitors did not have a significant effect on the risk of myocardial infarction or ischemic stroke while possibly increasing the risk of heart failure." (PMID 37920618, 2023).
heart failure (continued). "In addition, saxagliptin, which belongs to the class of DPP-4 inhibitors, exhibited a higher incidence of hospitalization due to heart failure." (PMID 37920618, 2023). "The FDA has provided warnings regarding the increased risk of heart failure events with DPP-4 inhibitors, but an updated meta-analysis showed no significant risk of heart failure events." (PMID 37686185, 2023). "Likewise, there seems to be little heterogeneity with respect to differences between various DPP-4 inhibitors (with the potential exception of their influence on heart failure-related hospitalizations)." (PMID 36473887, 2022). "Additionally, 288 (11.6%) DPP-4 inhibitor users and 270 (10.9%) metformin users developed heart failure." (PMID 36078917, 2022). "Dipeptidyl-peptidase-4 inhibition by sitagliptin has been reported to decrease collagen deposition, and activation of pro-fibrotic signaling in rat hearts potentially improves fibrosis in heart failure." (PMID 35884882, 2022). "Studies have reported that inhibition of DPP4 by pharmacological inhibitors alleviated fibrotic responses, such as in bleomycin-induced dermal and pulmonary fibrosis, CCl4-induced liver fibrosis, and a high-salt-diet-induced cardiac failure and fibrosis." (PMID 33117158, 2020). "Studies have found that DPP-4 inhibitor therapy did not increase the overall risk of major cardiovascular and renal outcomes but increased the hospitalization rate for heart failure." (PMID 31969144, 2020). "DPP-4 inhibition might exacerbate the clinical course of heart failure via pathways of SDF-1 (stromal cell-derived factor 1)/CaMKII (Ca2+/calmodulin-dependent protein kinase II)." (PMID 31969144, 2020). "It is also noteworthy that small clinical studies (< 50 patients) examining the CV effects of DPP-4 inhibitors, including linagliptin, have shown protective effects, including decreases in aortic PWV, improved microvascular function and lower heart failure risk compared to SU." (PMID 29669555, 2018). "A DPP-4 inhibitor is an oral anti-hyperglycemic agent that has many advantages, such as an antiarteriosclerotic effect and vascular endothelial function-improving effect, but increased hospitalizations due to heart failure have been noted." (PMID 29788955, 2018). "The findings with DPP-4 inhibitors also differ from the responses reported with SGLT2 inhibitors, which (in two trials) were reported to reduce major adverse cardiovascular events, especially the risk of new-onset heart failure." (PMID 29310647, 2018). "However, given the lack of consistency of the study results, more data will be helpful to further elucidate the question of DPP-4 inhibition and effect on heart failure." (PMID 29270438, 2017). "Data elucidating a potential role for DPP4 in heart failure (HF) have conflicted." (PMID 28587613, 2017). "These additional references suggest that certain risks like heart failure and related hospitalisation, and pancreatitis, may be increased with the use of DPP-4 inhibitors compared to other anti-diabetic treatments, independently of age group." (PMID 29047372, 2017). "There is controversy as to whether DPP-4 inhibitor therapy contributes to suppression of pathologic changes in heart failure." (PMID 28771625, 2017). "Because there remains clinical caution regarding DPP-4 inhibitor-induced heart failure, further experimental and clinical research is required to elucidate the precise mechanisms by which DPP-4 inhibitors affect diastolic function and heart failure in patients with T2DM." (PMID 28490337, 2017). "However, heart failure hospitalization rates for sitagliptin and alogliptin, also DPP4 inhibitors, were comparable to placebo in the TECOS and EXAMINE trials, respectively." (PMID 28756774, 2017). "DPP4 activities were similar in the investigated heart failure subgroups." (PMID 26544044, 2015). "Furthermore, DPP4 inhibitors showed a statistically significant increase in heart failure outcomes (RR = 1.16; 95% CI 1.01–1.33; P = 0.04)." (PMID 26075284, 2015).